FXYD2 (FXYD domain containing ion transport regulator 2)
Description:
May be involved in forming the receptor site for cardiac glycoside binding or may modulate the transport function of the sodium ATPase.
Synonyms: ATP1G1; MGC12372; HOMG2
Tractability: Small molecule: a drug acting on it is in phase 2 or 3 trials; a structure with a bound ligand is known; a high-quality ligand is known; it belongs to a druggable protein family. Antibody: its Gene Ontology location is reachable by antibodies, with high confidence; UniProt predicts a signal peptide or a membrane-spanning region.
Gene: Protein-coding gene on chromosome 11 (117,800,839 to 117,828,698, reverse strand). Ensembl gene ENSG00000137731.
Subcellular location: Membrane
Subcellular location (Human Protein Atlas): Mitochondria
Pathways (Reactome):
Disease: Potential therapeutics for SARS
Muscle contraction: Ion homeostasis
Transport of small molecules: Ion transport by P-type ATPases
Gene Ontology:
Molecular function: ATPase activator activity; protein-macromolecule adaptor activity; sodium channel regulator activity; ion channel regulator activity
Biological process: establishment or maintenance of transmembrane electrochemical gradient; positive regulation of sodium ion export across plasma membrane; potassium ion import across plasma membrane; proton transmembrane transport; sodium ion export across plasma membrane; transmembrane transport; cellular hyperosmotic salinity response; monoatomic cation transport; monoatomic ion transport; negative regulation of cell population proliferation; regulation of monoatomic ion transport
Cellular component: extracellular exosome; sodium:potassium-exchanging ATPase complex; plasma membrane; basolateral plasma membrane; membrane
Genetic constraint (gnomAD): Loss-of-function variants: 8 observed, 11.64 expected, observed/expected ratio (o/e) 0.69, 90% interval 0.4 to 1.24. The synonymous counts are far from expectation, so gnomAD's model fits this gene poorly and the ratio says little. Missense variants: 92 observed, 84.02 expected, observed/expected ratio (o/e) 1.1, 90% interval 0.92 to 1.3. Synonymous variants: 42 observed, 28.1 expected, observed/expected ratio (o/e) 1.49, 90% interval 1.16 to 1.87.
Gene-disease validity (ClinGen):
ClinGen rates the evidence that FXYD2 causes each of these diseases.
renal hypomagnesemia 2 (autosomal dominant): Moderate.
Homologues: Orthologues: chimpanzee FXYD2 (97% identical), pig FXYD2 (82% identical), dog FXYD2 (77% identical), rat Fxyd2 (76% identical), rabbit FXYD2 (73% identical), mouse Fxyd2 (71% identical), guinea pig FXYD2 (70% identical), tropical clawed frog fxyd2 (50% identical). Paralogues in human: FXYD6 (42% identical), FXYD1 (39% identical), FXYD5 (32% identical), FXYD3 (30% identical), FXYD4 (30% identical), FXYD7 (29% identical).
Diseases named in the same sentence as FXYD2 in open-access papers:
FXYD2 is named in the same sentence as 47 diseases in open-access papers, as found by Europe PMC text mining. Sharing a sentence is not in itself a finding about the gene and the disease. The quoted sentences say what the papers report.
Hypomagnesemia (8 papers, 2017 to 2025). An abnormally decreased magnesium concentration in the blood. "FXYD2 encodes the γ subunit of the Na+-K+-ATPase, and FXYD2 mutations are causative for hypomagnesemia." (PMID 35554666, 2022). "Overall, it is clear that hypomagnesemia with renal Mg wasting (and hypocalciuria) observed in these genetic diseases is associated with disruption of the normal Na,K‐ATPase–FXYD2 interaction." (PMID 30175537, 2018). "Only three families, all Belgian or Dutch, putatively descendants from a common founder, have been reported to carry the hypomagnesemia-causing FXYD2 mutation." (PMID 27234911, 2017). "In line with this, mutations in the human FXYD2 gene cause hypomagnesemia." (PMID 37154155, 2023). "This in turn would influence FXYD2 transcription, causing hypomagnesemia." (PMID 27234911, 2017). "Several members of the FXYD family have been linked to major human diseases, including heart failure (FXYD1), hypomagnesemia (FXYD2), cancer (FXYD3, FXYD5), and schizophrenia (FXYD6), making them attractive specific targets for future therapies." (PMID 40428357, 2025). "Mutations in FXYD2 (G41R), and transcription factors (HNF‐1B and PCBD1) that affect FXYD2 expression are associated with hypomagnesemia with hypermagnesuria." (PMID 30175537, 2018).
diabetes (6 papers, 2017 to 2023). "Furthermore, common genetic variation in magnesium regulating genes TRPM6, CLDN19, SLC41A2, CNNM2 and FXYD2 significantly modify the risk of diabetes through serum magnesium levels." (PMID 28224192, 2017). "Future studies are needed to validate the contribution of the HNF1A/FXYD2 pathway to diabetes and to explore options to manipulate β-cell heterogeneity for clinical uses." (PMID 37669939, 2023). "Genetic variation in CLDN19, CNNM2, FXYD2, SLC41A2, and TRPM6 significantly influenced diabetes risk (p < 0.05), and for CNNM2, FXYD2, SLC41A2 and TRPM6 this risk was completely mediated by serum magnesium levels." (PMID 28224192, 2017). "Genetics seems to be a vital risk factor for Type 2 diabetes, and serum magnesium levels may modify the risk of diabetes through several magnesium-regulating genes such as TRPM6, CLDN19, SLC41A2, CNNM2, and FXYD2." (PMID 35565766, 2022). "However, there is a suspicion that FXYD2 may not be important for β-cell dysfunction in diabetes since it is not genetically associated to T2D57." (PMID 37669939, 2023).
ovarian carcinoma (4 papers, 2016 to 2023). A malignant neoplasm originating from the surface ovarian epithelium. "As previously reported, silencing FXYD2 expression in ovarian cancer cells resulted in the inhibition of Na+/K+-ATPase activity induced by increased sensitivity to cardiac glycosides, which are Na+/K+-ATPase inhibitors." (PMID 34270462, 2021). "Compared with other ovarian cancer subtypes and normal ovarian surface epithelia, FXYD2 was highly expressed in OCCC." (PMID 26910837, 2016). "Next, we assessed FXYD2 protein and mRNA levels in clinical ovarian cancer specimens using immunohistochemistry and qRT-PCR, respectively." (PMID 26910837, 2016). "We show that FXYD2 status correlated strongly with clear cell histology in both analyses of clinical ovarian cancer specimens (P < 0.0001)." (PMID 26910837, 2016). "Immunohistochemical analysis of 144 ovarian cancer tissues indicated that OCCC samples displayed a significantly higher percentage of cells that stained positive for FXYD2 compared with other ovarian cancer subtypes, with high FXYD2 expression observed in the membrane." (PMID 26910837, 2016). "Additionally, high expression of the FXYD2 gene is closely related to ovarian clear cell carcinoma, which is a highly lethal ovarian cancer subtype, and the use microfluidic chip can achieve rapid, sensitive, specific and quantitative detection of the FXYD2 gene." (PMID 38111049, 2023). "Hsu IL reported that FXYD2 was transcriptionally regulated by the transcription factor HNF1B, functioning in tumor growth via autophagy-mediated cell death and modulating the affinity of Na+/K+-ATPase in ovarian cancer." (PMID 34270462, 2021). "High expression of FXYD2 in OCCC but not in other subtypes of epithelial ovarian cancers and normal ovarian tissues is attributed to the transcriptional upregulation of HNF1B." (PMID 26910837, 2016). "High levels of FXYD2 were detected in OCCC but not in normal ovarian tissues or in other subtypes of epithelial ovarian cancers." (PMID 26910837, 2016).
ovarian clear cell cancer (4 papers, 2016 to 2025). An invasive malignant neoplasm that arises from the ovary and is characterized by a predominance of clear and hobnail malignant epithelial cells. "Interestingly, while FXYD2 is downregulated in ccRCC, it is upregulated in other tumor types, such as colorectal, hepatocellular, and ovarian clear cell carcinomas, where its high expression correlates with advanced disease and poor prognosis." (PMID 40723891, 2025). "Study demonstrated FXYD2 was a therapeutic target in ovarian clear cell carcinoma." (PMID 36313180, 2022).
type 2 diabetes (4 papers, 2022 to 2025). "One interpretation of the data is that altered FXYD2 expression is a major cause of beta cell dysfunction in type 2 diabetes." (PMID 35482056, 2022). "However, FXYD2 does not appear to be genetically associated with type 2 diabetes risk or beta cell function as one would expect if altered FXYD2 expression was of major importance for beta cell dysfunction." (PMID 35482056, 2022).
cholangiocarcinoma (3 papers, 2014 to 2024). A carcinoma that arises from the intrahepatic biliary tree (intrahepatic cholangiocarcinoma) or from the junction, or adjacent to the junction, of the right and left hepatic ducts (hilar cholangiocarcinoma). "For instance, FXYD2 is differentially expressed in cholangiocarcinoma cells, as is FXYD5 in epithelioid sarcoma, head and neck squamous cell carcinoma, small cell carcinoma, pancreatic cancer cells and breast cancer cells." (PMID 25013464, 2014).
Hypertension (3 papers, 2014 to 2019). The presence of chronic increased pressure in the systemic arterial system. "However, FXYD2-knockout-mice were resistant to sodium retention and protected from salt-induced hypertension." (PMID 31083566, 2019).
schizophrenia (3 papers, 2022 to 2025). A major psychotic disorder characterized by abnormalities in the perception or expression of reality. "Two pathogenic de novo variants in ATP1A3 and missense variants in FXYD gene family (FXYD1, FXYD2) were also identified in 17 sporadic cases of childhood onset schizophrenia using whole exome sequencing." (PMID 36384485, 2022).
glioma (2 papers, 2021 to 2023). A benign or malignant brain and spinal cord tumor that arises from glial cells (astrocytes, oligodendrocytes, ependymal cells). "Specifically, higher degree malignancies are associated with lower FXYD2 mRNA expression, suggesting that FXYD2 mRNA expression can be used as a predictive biomarker for the degree of malignancy of gliomas." (PMID 34753441, 2021). "Moreover, FXYD2 mRNA expression was found to be related to the survival time of glioma patients with lower expression associated with shorter survival time, suggesting that it can also be used to predict patient survival prognosis." (PMID 34753441, 2021). "Kaplan–Meier survival curves were used to explore the effect of FXYD2 mRNA expression on the total survival time of glioma patients." (PMID 34753441, 2021). "Subgroup analysis showed that different subgroups of glioma patients with high FXYD2 mRNA expression also had longer OS." (PMID 34753441, 2021). "Using Kaplan–Meier survival curves, it was confirmed in two independent databases that glioma patients with high FXYD2 mRNA expression had a longer survival time than patients with low expression from TCGA (P = 0.000) and REMBRANDT database (P = 0.000)." (PMID 34753441, 2021). "FXYD2 mRNA expression in glioma patients with different clinical and molecular pathological features was compared using a scatter plot." (PMID 34753441, 2021). "This study revealed that the expression of FXYD2 mRNA is related to the degree of malignancy of gliomas." (PMID 34753441, 2021). "The 516 glioma patients were then classified as having low or high FXYD2 mRNA expression based on median expression values." (PMID 34753441, 2021). "Clinical features, FXYD2 mRNA expression levels, and survival data were analyzed for 516 glioma patients from the Chinese Glioma Genome Map Project, 481 from the cancer genome map datbase and 268 from the molecular braintumor database." (PMID 34753441, 2021). "Further subgroup analysis on the two independent datasets showed that patients with low- or high-grade gliomas that had high FXYD2 mRNA expression also exhibited longer survival times." (PMID 34753441, 2021). "This study revealed that the expression of FXYD2 mRNA in gliomas can predict the degree of malignancy and survival time of patients." (PMID 34753441, 2021). "The expression patterns for FXYD2 mRNA were compared using the chi-square test, and overall survival (OS) of glioma patients was evaluated according to FXYD2 mRNA expression levels." (PMID 34753441, 2021). "Here, we analyze the expression of FXYD2 mRNA in gliomas, and explore its clinical prognostic value and significance in this disease." (PMID 34753441, 2021). "At the same time, FXYD2 mRNA expression can predict the chemosensitivity of glioma patients to TMZ." (PMID 34753441, 2021). "FXYD2 mRNA expression was also related to the chemosensitivity of glioma patients to TMZ." (PMID 34753441, 2021). "Here, through transcriptome sequencing, this study sought to establish the relationship between FXYD2 mRNA expression and the clinical features and survival data for glioma cases collected from the Chinese Glioma Genome Map Project as well as TCGA and REMBRANDT databases." (PMID 34753441, 2021). "FXYD2 mRNA expression represents a new independent factor affecting the survival of glioma patients and may serve as an independent prognostic indicator to predict the sensitivity of gliomas to TMZ." (PMID 34753441, 2021). "Moreover, the survival time for glioma patients with high FXYD2 mRNA expression was longer." (PMID 34753441, 2021). "Meanwhile, TMZ represents an independent factor affecting the survival of glioma patients with high expression of FXYD2 mRNA, but not patients with low expression." (PMID 34753441, 2021). "However, the expression pattern and clinical significance of FXYD2 have not yet been reported in gliomas." (PMID 34753441, 2021).
glioma (continued). "However, in the group with low FXYD2 mRNA expression, chemotherapy status was not an independent factor affecting the survival of patients with glioma (univariate Cox analysis P = 0.132; multivariate Cox analysis P = 0.174)." (PMID 34753441, 2021). "However, the expression and application value of FXYD2 mRNA in gliomas have not been previously reported." (PMID 34753441, 2021).
heart failure (2 papers, 2024 to 2025). Inability of the heart to pump blood at an adequate rate to meet tissue metabolic requirements. "Other important up-regulated genes were Fxyd2 (FXYD domain-containing ion transport regulator 2), an important regulator of the Na+ transport, and Itgb6 (myo-inositol 1-phosphate synthase A1), involved in resynchronization following heart failure." (PMID 38534766, 2024).
Hypocalciuria (2 papers, 2018 to 2020). An abnormally decreased calcium concentration in the urine. "Note that hypocalciuria associated with the FXYD2 G41R mutation is not easily explained and reveals complexity of the mechanism." (PMID 30175537, 2018).
angiosarcoma (1 paper, 2016). A malignant tumor arising from the endothelial cells of the blood vessels. "Most interestingly, expression of FXYD2 and FXYD4 genes is modified in angiosarcoma vs control human samples." (PMID 27716384, 2016).
clear cell renal cell carcinoma (1 paper, 2022). "However, the specific role of FXYD2 in clear cell renal cell carcinoma (ccRCC) remains unknown." (PMID 36313180, 2022).
cocaine abuse (1 paper, 2023). Disorders related or resulting from use of cocaine. "We found that FXYD2 and DRD2 mRNA expression was inversely correlated in both mouse purified iMSNs and human postmortem caudate (whole-tissue RNAseq) of individuals with severe cocaine abuse history and control subjects." (PMID 37881572, 2023).
colon cancer (1 paper, 2021). "The expression of FXYD2, FXYD3 and FXYD4 is an independent prognostic factor for for the survival of colon cancer." (PMID 34753441, 2021).
dependent (1 paper, 2025). "Expected intrafamilial variability in clinical manifestations highlights the need for further follow-up, as additional patients and families with FXYD2-dependent tubulopathy are reported." (PMID 40428357, 2025).
gallstones (1 paper, 2022). Solid crystalline precipitates in the biliary tract, usually formed in the gallbladder, resulting in the condition of cholelithiasis. "We found that the SNP rs869789, which located in the 3′ UTR region of FXYD2, were consistently significantly associated gallstone in the subgroup analyses." (PMID 35651949, 2022). "These loci are located in seven different genes, including SLC4A5, MUC4, FTO, NPC1 and FXYD2 genes that may increase the risk of gallstone in the Tibetan population, while CFTR and ADCY2 genes that reduce the risk of gallstone in the Tibetan population." (PMID 35651949, 2022).
Hypokalemia (1 paper, 2025). An abnormally decreased potassium concentration in the blood.
leukemia (1 paper, 2022). A malignant (clonal) hematologic disorder, involving hematopoietic stem cells and characterized by the presence of primitive or atypical myeloid or lymphoid cells in the bone marrow and the blood. "We identified 147 CRGs from 153 leukemia samples with only five observed in more than one sample (CEP164, DSCAML1, FXYD2, SIK3, and GRIA4)." (PMID 35945623, 2022).
peripheral nerve lesion (1 paper, 2023). "Indeed, after peripheral nerve lesions or inflammation, FXYD2 has been shown to reduce the activity of this pump and to allow persistent neuronal hyperexcitability notably of the so-called non-peptidergic IB4-positive nociceptive population." (PMID 37154155, 2023).
renal cell carcinoma (1 paper, 2021). "In recent years, researchers have found that FXYD2 shows different expression patterns in different kinds of renal cell carcinoma as defined by immunohistochemistry." (PMID 34270462, 2021).
SARS-CoV infections (1 paper, 2022). "It was found that 45.87% of the associated genes (CASP3, CASP9, MAPK1, MAPK3, XIAP) contributed to cytochrome C-mediated apoptotic response and 3.67% of the associated genes (BECN1, FXYD2, GSK3B, HSP90AA1, ITGB1, MAP1LC3B) contributed to SARS-CoV infections." (PMID 36164436, 2022).
serous carcinoma (1 paper, 2016). "High FXYD2 expression was also observed by qRT-PCR analysis in OCCC samples (mean: 1.7159, n = 46) compared with serous carcinoma samples (mean: 0.0006, n = 28, P = 0.004)." (PMID 26910837, 2016).